RARA (retinoic acid receptor alpha)
Diseases named in the same sentence as RARA in open-access papers (continued):
Sharing a sentence is not in itself a finding about the gene and the disease.
leukemia (continued). "With the exception of leukemia, according to The Cancer Genome Atlas, most cancers, including breast cancer, carry many genetic alterations but not RARA mutations, even if they all display resistance to physiological RA anticancer action." (PMID 27894085, 2016). "The effect of oridonin in increasing the levels of RARα protein could be clearly seen in primary leukemia cells from the bone marrow of three AML patients." (PMID 25886043, 2015). "As expected, TNFα treatment also strongly increased RARα expression, which may account, at least in part, for TNFα-induced differentiation in some leukemia cells." (PMID 25886043, 2015). "We investigated whether activated STATs may mediate response to ATO treatment not only in PML/RARα but also in DEK/NUP214-positive leukemia." (PMID 25568664, 2014). "Ectopic expression of PML/RARα and PLZF/RARα in hematopoietic cells mimics the leukemic phenotype by inducing a differentiation block and an aberrantly activated self-renewal capability, leading to the development of leukemia in mice." (PMID 23152790, 2012). "However, the use of PCR in leukemia is limited because only several types of leukemia have specific gene markers such as PML/RARa, AML1/ETO, and bcr/abl." (PMID 23691459, 2012). "As some studies have shown, RARα and RARγ may be involved in apoptosis induction in immortalized keratinocytes and leukemia cells." (PMID 18166136, 2007). "However, based on murine APL models, it appears that PML/RARα alone is not sufficient to cause leukemia, and cooperating events are required for the development of APL." (PMID 33298855, 2020). "RARA could interact with Myc and regulate RARA-dependent genes expression in leukemia cells." (PMID 30123134, 2018). "Pharcin B induces myeloid differentiation in combination with ATRA in several AML cell lines and primary leukemia samples, enhancing ATRA-dependent transcriptional activity of RARα, which contributes to this effect." (PMID 41590345, 2026). "CS1 and CS2 demonstrated suppression of leukemia proliferative activity and immune evasion, cancer cell viability, and leukemia stem cell renewal via MYC, CEBPA, and RARA axis." (PMID 41157107, 2025). "Both FB23 and FB23-2 suppress leukemia progression by selectively blocking FTO and restoring the m6A profile of MYC, CEBPA, RARA, and ASB2 genes." (PMID 41157107, 2025). "The use of small-molecule inhibitors targeting FTO affected the expression levels of downstream genes such as MYC, CEBPA, RARA, and ASB2, thereby exerting anti-leukaemia effects." (PMID 39641872, 2024). "RA acts on the RARA moiety of PML-RARA fusion protein that will be degraded, and contributes leukemia cells to terminal differentiation and apoptosis." (PMID 35488254, 2022). "Here, we investigated the role and mechanism of TBLR1-RARα, a rare RARα fusion gene, on ATO treatment in leukemia cells." (PMID 35517404, 2022). "Collectively, our results indicate that EGCG reduced leukaemia burden, induced apoptosis and differentiation thus resulting in a longer survival of PML/RARα mice." (PMID 33907248, 2021). "By regulating the expression of the leukemia-related oncogenes ASB2 and RARA, FTO overexpression can downregulate the total level of m6A, promote cell growth and colony formation in vitro, and promote the occurrence of leukemia in vivo." (PMID 34381710, 2021). "The inhibition of RA signaling with the pan-RARA inverse agonist, BMS493, reduced the leukemia burden of CLL cells in vitro and in vivo." (PMID 31805753, 2019). "ASB2 (ankyrin repeat and SOCS box containing 2) and RARA (retinoic acid receptor alpha) are induced during hematopoiesis and function as crucial regulators of ATRA-induced differentiation of leukemia cells." (PMID 29439529, 2018). "PCR and FISH analyses performed during diagnosis showed that patient OM110223’s leukemia cells present a short bcr3 transcript which connects exon 3 of the PML gene and exon 9 of the RARA gene (equivalent to the exon 3 of the RARA-001 ENSEMBL transcript)." (PMID 29623188, 2017).
leukemia (continued). "We found that the L-IC of PML/RARα-positive leukemia is different from the L-MC, as already described for DEK/NUP214-positive leukemia." (PMID 25568664, 2014). "The cells originating from the PML/RARα-, RUNX1/RUNX1T1- or DEK/NUP214-positive LT-HSCs induced leukemia with a high penetrance of 70%, 50% or 80%, respectively." (PMID 25568664, 2014). "For some of the genes involved, including MLL, PML, RARA and AML1 (RUNX1) a relatively large number of translocation breakpoints from de novo and therapy related leukemia cases have been determined at the base pair level." (PMID 22829791, 2012). "FTO enhances leukemogenesis and leukemia oncogene-mediated cell transformation by reducing m6A levels on mRNA transcripts of targets such as ASB2 and RARA, thereby regulating their expression and inhibiting all-trans retinoic acid (ATRA)-induced differentiation of AML cells." (PMID 39295872, 2024). "In addition, the mechanisms of ATO cytotoxicity also rely in degradation of the leukemia fusion protein, namely PML-retinoic acid receptor alpha (PML-RARα) restoring PML functions." (PMID 29467594, 2018). "The sequencing results of PML-RARA chRNA qPCR amplifications revealed another fusion transcript joining PML exon 3 and RARA exon 10 present in OM110223 leukemia cells, without corresponding spanning junction read." (PMID 29623188, 2017). "Taken together with our previous report that HF blocked NB4 proliferation and reduced the leukemia burden in vivo we postulated that despite the interference of PML/RARα with TFβR1/SARA/SMAD2/3 complex, the TGF-β pathway remain active in APL and contributes for leukemia progression." (PMID 26099922, 2015). "In summary, these data show that the AAFPs PML/RARα and DEK/NUP214 initiate leukemia by transforming a small subpopulation of LT-HSCs, but both maintain already established leukemia from already committed cell populations in the BM suggesting a difference between L-ICs and L-MCs." (PMID 25568664, 2014). "PML/RARα transgenic murine APL models mimic this notion well, in which PML/RARα only does not induce leukemia (PML/RARα transgenic preleukemic mice) and additional secondary events cooperating with PML/RARα promote APL development (PML/RARα transgenic APL mice)." (PMID 33298855, 2020). "Notably, the cooperative ability of ATO and ATRA to eliminate TICs in TNBC by targeting Pin1 is consistent with the previous findings that genetic or chemical inhibition of Pin1 induces PML/RARα degradation to eradicate leukemia stem cells and treat APL without inducing myeloid differentiation." (PMID 30093655, 2018). "The hypothesis that TRIB1 and PML/RARA cooperate has been tested and, while they do not cooperate to drive a shorter latency leukemia in vivo, TRIB1 and PML/RARA have functionally redundant inhibitory effects on C/EBPα, which also impacts responses to therapeutic All-Trans Retinoic Acid (ATRA)." (PMID 27908682, 2017). "The exact mechanism is still unknown and there are some putative mechanisms for this phenomenon involving in overexpression of MN1, mutations of RARa as noted in HL-60 cells, selection of non-APL leukemia clones and increased expression of proteins involved in ATRA's metabolism." (PMID 19435509, 2009). "Post-treatment bone marrow displayed no residual leukemia by flow cytometry; however, FISH for PML/RARA still displayed a high percentage of the same atypical signal pattern." (PMID 39596602, 2024).
acute myeloid leukemia (178 papers, 2006 to 2026). Acute myeloid leukemia (AML) is a group of neoplasms arising from precursor cells committed to the myeloid cell-line differentiation. "Moreover, genes targeted by both PU.1 and PML/RARα were significantly involved in categories associated with oncogenesis, hematopoiesis and the pathogenesis of acute myeloid leukemia." (PMID 23547873, 2013). "In other BTB domain-containing fusion-positive cancers, such as PLZF/Retinoic Acid Receptor alpha (RAR alpha) that causes Acute Myeloid Leukemia (AML), disruption of the BTB domain also abrogates oligomer formation and fusion protein functions." (PMID 38935636, 2024). "We previously found that PIR mRNA expression is silenced by the acute myeloid leukemia (AML)-associated fusion proteins PML/RARα and AML1/ETO both in cellular models and in primary blasts form AML patients." (PMID 20089166, 2010). "The retinoic acid receptor-α agonist SY-1425 can promote the differentiation of acute myeloid leukemia cells with high expression of RARA or IRF8 genes, thereby inhibiting tumor growth." (PMID 40672386, 2025). "The typical genomic feature of acute myeloid leukemia (AML) M3 subtype is the fusion event of PML/RARα, and ATRA/ATO-based combination therapy is current standard treatment regimen for M3 subtype." (PMID 38322990, 2024). "KIT is a well-established oncogene, particularly in acute myeloid leukemia (AML) where mutations play a large role in pathology, and RARA is involved in embryonic development whose disruption is well established in carcinogenesis." (PMID 37805590, 2023). "A key role of 5‐LO for the maintenance of leukemic stem cells was also shown in a PML/RARα‐positive stem cell model of acute myeloid leukemia." (PMID 33205517, 2021). "The most common acute myeloid leukemia-associated fusion protein, AML1/ETO, forms a complex with RARα and promotes a repressed chromatin conformation at the RARβ2 regulatory regions." (PMID 28230720, 2017). "We demonstrate applications in large-scale disease studies, by identifying PTDs in MLL, ITDs in FLT3, and reciprocal fusions between PML and RARA, in two deeply sequenced acute myeloid leukemia (AML) RNA-seq datasets." (PMID 23941359, 2013). "SKI also blocks differentiation by inhibiting RARα signaling in some subtypes of acute myeloid leukemia." (PMID 22194822, 2011). "Chromosomal translocations can lead to the formation of chimeric genes encoding fusion proteins such as PML/RARα, PLZF/RARα, and AML-1/ETO, which are able to induce and maintain acute myeloid leukemia (AML)." (PMID 21811629, 2011). "Additionally, Syros Pharmaceuticals has utilized its gene control platform to identify acute myeloid leukemia patients and subgroups of myelodysplastic syndrome with SEs of RARA or IRF8 genes and discovered biomarkers that can recognize these SEs." (PMID 40672386, 2025). "It was also discovered that recombinant human insulin-like growth factor-binding protein 7 (rhIGFBP7) triggers the ATRA-driven eradication of leukemia stem/progenitor cells in acute myeloid leukemia (AML) with elevated retinoic acid receptor α gene (RARA) expression." (PMID 38671875, 2024). "APL, an M3 variant of acute myeloid leukemia (AML), expresses a fusion oncogene (a fusion of PML gene with RARα gene), leading to translation of the PML/RARα chimeric protein, which blocks hematopoietic progenitor cell differentiation and ultimately leads to APL." (PMID 39253293, 2024). "Moreover, FTO promotes proliferation of AML cells through targeting of the ASB2 and RARA in acute myeloid leukemia cells." (PMID 31333841, 2019).
acute myeloid leukemia (continued). "APL is a subtype of acute myeloid leukemia (AML) that is genetically characterized by a specific chromosomal translocation that yields the promyelotic leukemia/retinoic acid receptor alpha (PML/RARA) fusion gene—a DNA-binding transcription factor." (PMID 29206204, 2017). "RARα takes part in regulation of VDR transcription, and unliganded RARα acts as a transcriptional repressor to VDR gene in acute myeloid leukemia (AML) cells." (PMID 28635660, 2017). "In line with this, we could show that pharmacological inhibition of 5-LO by CJ-13,610 also affects the aberrant stem cell capacity in a PML/RARα-positive model of AML (acute myeloid leukemia) and a murine cancer stem cell (CSC) model." (PMID 39268466, 2024). "In acute myeloid leukemia, FTO was shown to control stem cell differentiation through the ASB2/RARA axis, and FTO was revealed to affect immunotherapy by regulating intracellular factors (PD-1, CXCR4, and SOX10) in melanoma." (PMID 38384328, 2024). "FTO can downregulate the expression of ASB2 and RARA by reducing m6A levels in UTRs of transcripts, resulting in the inhibition of ATRA-mediated acute myeloid leukemia (AML) cell differentiation." (PMID 37178254, 2023). "Studies have reported its high expression in acute myeloid leukemia (AML), promoting cellular transformation and proliferation by the post-transcriptional regulation of ASB2, RARA, MYC, and CEBPA." (PMID 36371254, 2022). "Additionally, through mapping SEs in Acute Myeloid Leukemia (AML), a subtype of AML cells with SE-driven RARα was identified to be sensitive to RARα agonist SY-1425." (PMID 35740532, 2022). "FTO played an oncogenic role in acute myeloid leukemia through regulating target genes such as ASB2 and RARA by reducing m6A levels in these mRNA transcripts." (PMID 32111213, 2020). "The interaction of S100A3 with RARα is direct and in lung cancer, APL and acute-myeloid-leukemia (AML) cells." (PMID 30532072, 2019). "Specimens included twelve APL specimens at initial diagnosis with PML::RARA fusion by standard-of-care genetic tests and six acute myeloid leukemia specimens without PML::RARA fusion." (PMID 39766302, 2024). "In specific subtypes of acute myeloid leukemia (AML), elevated FTO levels decrease m6A levels in ASB2 and RARA mRNA transcripts, thereby promoting their expression." (PMID 40000966, 2025). "A study found that several vital oncogenes in acute myeloid leukemia (AML), such as AML1-ETO, PML/RARa, and PLZF/RARa, induce leukemogenesis by activating c-Myc." (PMID 38611876, 2024). "PRAME is a dominant repressor of retinoic acid (RA) signaling in melanoma and acute myeloid leukemia (AML) by interaction with the Enhancer of Zeste Homolog 2 (EZH2) and the RA receptor α (RARα) at RA response elements (RAREs)." (PMID 39550391, 2024). "Recurrent gene rearrangements are present in 30–40% of acute myeloid leukemia (AML), and well-described driver fusions sometimes suffice to diagnose leukemias (for example, PML::RARA, or RUNX1::RUNX1T1 among others)." (PMID 37699001, 2023). "m6A demethylase FTO is highly expressed and plays a critical oncogenic role in acute myeloid leukemia (AML) by targeting a cohort of critical transcripts, such as ankyrin repeat and SOCS box-containing 2 (ASB2) and retinoic acid receptor alpha (RARA)." (PMID 36835633, 2023). "FTO can downregulate the expression of ASB2 and retinoic acid receptor alpha (RARA) by reducing m6A levels in UTRs of transcripts, resulting in the inhibition of all-trans retinoic acid (ATRA)-mediated acute myeloid leukemia (AML) cell differentiation." (PMID 37151887, 2023). "In a landmark study, overexpression of FTO promoted leukemia progression and inhibited all-trans-retinoic acid-induced acute myeloid leukemia (AML) differentiation by reducing m6A levels in ASB2 and RARA mRNA." (PMID 37916161, 2023).
acute myeloid leukemia (continued). "For instance, the overexpression of FTO in acute myeloid leukemia (AML) can inhibit the m6A levels of Ankyrin repeat and SOCS box containing 2 (ASB2) and of retinoic acid receptor α (RARα) mRNA, resulting in the occurrence and progression of AML." (PMID 33643384, 2021). "FTO acted as an oncogene in acute myeloid leukemia (AML) through regulating target genes such as ASB2 and RARA by reducing m6A levels in these mRNA transcripts." (PMID 32209098, 2020). "Previous study reported that FTO was highly expressed and functioned as an oncogene in certain subtypes of acute myeloid leukemia (AML) by targeting ASB2 and RARA through mRNA demethylation." (PMID 31143705, 2019). "APL is a distinct subtype of acute myeloid leukemia (AML), and 98% of these patients have balanced reciprocal translocations between chromosomes 15 and 17 that result in the fusion of the promyelocytic leukemia (PML) and retinoic acid receptor α (RARα) gene." (PMID 22134377, 2012). "This last designation is in contrast to the WHO, which still requires blast counts of at least 20% for a diagnosis of acute myeloid leukemia (AML) in the absence of certain specific AML-defining genetic abnormalities (e.g., PML::RARA fusion, RUNX1::RUNX1T1 fusion, etc)." (PMID 39941875, 2025).